RIPPLY3 (ripply transcriptional repressor 3)
Description:
Acts as a transcriptional corepressor. Negative regulator of the transcriptional activity of TBX1. Plays a role in the development of the pharyngeal apparatus and derivatives (By similarity).
Synonyms: DSCR6
Tractability: No criterion of Open Targets' tractability assessment is met for any kind of drug.
Gene: Protein-coding gene on chromosome 21 (37,006,150 to 37,019,662, forward strand). Ensembl gene ENSG00000183145.
Subcellular location: Nucleus
Gene Ontology:
Molecular function: protein binding
Biological process: embryonic pattern specification; negative regulation of transcription by RNA polymerase II; heart development; pharyngeal system development
Cellular component: nucleus
Genetic constraint (gnomAD): Loss-of-function variants: 8 observed, 8.77 expected, observed/expected ratio (o/e) 0.91, 90% interval 0.53 to 1.61. That is too few expected variants to judge how well the gene tolerates losing a copy. Missense variants: 262 observed, 228.14 expected, observed/expected ratio (o/e) 1.15, 90% interval 1.04 to 1.27. Synonymous variants: 99 observed, 93.81 expected, observed/expected ratio (o/e) 1.06, 90% interval 0.9 to 1.25.
Homologues: Orthologues: chimpanzee RIPPLY3 (98% identical), macaque RIPPLY3 (90% identical), dog RIPPLY3 (63% identical), rabbit RIPPLY3 (57% identical), mouse Ripply3 (54% identical), rat Ripply3 (51% identical), tropical clawed frog ripply3 (26% identical), zebrafish ripply3 (21% identical). Paralogues in human: RIPPLY1 (22% identical), RIPPLY2 (19% identical).
Diseases named in the same sentence as RIPPLY3 in open-access papers:
RIPPLY3 is named in the same sentence as 9 diseases in open-access papers, as found by Europe PMC text mining. Sharing a sentence is not in itself a finding about the gene and the disease. The quoted sentences say what the papers report.
Down syndrome (3 papers, 2019 to 2025). "As RIPPLY3 (DSCR6) is one of the genes in the supernumerary region of chromosome 21, we also speculate its ectopic expression in this context could be one contributing factor to the high incidence of CHDs in children with Down syndrome." (PMID 31091225, 2019).
DiGeorge syndrome (2 papers, 2025). "Additionally, the mechanism involving Ripply3 connects DS with DiGeorge syndrome, another disorder with similar facial changes, suggesting shared pathways behind some features of both conditions." (PMID 40982554, 2025). "Then, we identified the role of the transcription factor Ripply3 overdosage in midface shortening through the downregulation of Tbx1, another transcription factor involved in the CF midface phenotype encountered in DiGeorge syndrome." (PMID 40982554, 2025). "RIPPLY3 was characterized as a transcriptional co-repressor known to be regulating TBX1, a major gene involved in DiGeorge syndrome." (PMID 40003558, 2025).
Tetralogy of Fallot (1 paper, 2025). A congenital cardiac malformation comprising pulmonary stenosis, overriding aorta, ventricular septum defect, and right ventricular hypertrophy. "As such, some DS heart defects, such as the tetralogy of Fallot observed in some individuals, may be related to Ripply3-dependent downregulation of Tbx1, whereas in DGS, they are caused by the direct Tbx1 haploinsufficiency." (PMID 40982554, 2025).
cancer (1 paper, 2022). A tumor composed of atypical neoplastic, often pleomorphic cells that invade other tissues. "Although no direct studies have proved that RIPPLY3 (also known as DSCR6) is closely related to PTC or other malignant tumours, current studies have found that the RIPPLY3 gene plays a role in developing the pharynx and its derivatives in vertebrates." (PMID 35372518, 2022).
RIPPLY3 also shares sentences with these, for which no sentence is quoted: colorectal cancer (1 paper); conotruncal heart defect (1); leukaemia (1); Patent ductus arteriosus (1); thrombosis (1).